CXCL10 (C-X-C motif chemokine ligand 10)
Diseases named in the same sentence as CXCL10 in open-access papers (continued):
Sharing a sentence is not in itself a finding about the gene and the disease.
glioma (continued). "In the glioma mouse model, celecoxib treatment decreased protein expression and mRNA levels of Ccl2, CxcL10, and Cxcr3, both in the tumoral and peri-tumoral tissue." (PMID 35269652, 2022). "In the context of cancer immunotherapy, CXCL10 enhanced dendritic cell-antigen presentation and subsequent tumor cell killing by T cells in the presence of tumor vaccines in melanoma and glioma models." (PMID 34045467, 2021). "Pro‐inflammatory factors have been described in glioma, and it is generally considered that IL‐6, IL‐8, CXCL1, CXCL10 and TGFβ2 are pro‐tumour cytokines closely related to glioma progression." (PMID 34216174, 2021). "For glioma cells with IDH mutations, targeting mutant IDH can restore the release of CXCL10 and inhibit the production of PD-L1, promoting recruitment and tumor recognition of CTLs and inhibiting Tregs." (PMID 34211978, 2021). "The STAT3 inhibitor can target the central nervous system tumor by induing immunocyte tumor homing in a CXCL10-dependent manner." (PMID 34603309, 2021). "A previous study suggested that the expression of chemokine receptor/ligand pairs such as CXCR3/CXCL10 plays an important role in the proliferation of glioma cells." (PMID 32943658, 2020). "It is via JAK-STAT pathway that over expression of long non-coding RNA 135528 in glioma cells results in upregulation of interferon-gamma-inducible protein 10 (IP-10) that is also known as C-X-C motif chemokine 10 (CXCL10)." (PMID 32714456, 2020). "On the other hand, in the mouse glioma model, the high protein and mRNA level of Ccl2, Cxcl10 and Cxcr3 were decreased by celecoxib." (PMID 32943658, 2020). "In glioma cells, for example, the expression of CXCL10 is significantly upregulated when compared with healthy astrocytes and has been shown to increase cell proliferation by acting on CXCR3 in an autocrine manner." (PMID 31216755, 2019). "The CXCL10/CXCR-3 axis has been shown to be expressed in glioma cells, and NFATc3 dependent regulation of CXCR3 is on line with the role of this receptor in migration and site specific dissemination in many cancerous cells." (PMID 31249342, 2019). "The use of celecoxib alone was able to enhance expression of CXCL10 and increase recruitment of cytotoxic lymphocytes to the tumors in a pre-clinical glioma model." (PMID 30740109, 2018). "Our group and others have found that CXCR3, along with its ligands CXCL9 and CXCL10, plays predominant roles in cytotoxic lymphocyte trafficking into the glioma tumor site." (PMID 30740109, 2018). "Expression analysis of cytokines secreted by glioma cells co-cultured with MCs, revealed a significant increase in expression of CXCL10, CXCL12 and TNF-α." (PMID 28445977, 2017). "CXCL10/IP-10 has also been reported to promote colon cancer metastasis and to enhance tumorigenesis in basal cell carcinoma and human glioma." (PMID 26379707, 2015). "Other chemokines and cytokines known to be involved in glioma progression, such as CCL2, CXCL10 and IL-6, are selectively upregulated in the glioma-bearing hemisphere, and these increases are strongly reduced in EE mice." (PMID 25818172, 2015). "MCP-1 and CXCL10 were detected at high levels in glioma-conditioned supernatants compared to standard culture media (p<0.01)." (PMID 22496835, 2012). "This supports the notion of CXCL10 as an oncogene in glioma." (PMID 38461458, 2024). "Furthermore, we found that calycosin inhibited proliferation, migration, and invasion in U87 and U251 glioma cells, and decreased CXCL10 expression in a dose-dependent manner, along with its downstream effectors such as NLRP3, NF-κB, and IL-1β." (PMID 38461458, 2024). "C-X-C chemokine ligand 10 (CXCL10), an inflammatory chemokine, has been reported to be related to the pathogenesis of cancer while it has not yet been linked to glioma." (PMID 38461458, 2024). "Similarly, in our 24 paired human glioma samples, CXCL10 expression increased with glioma grades and was more pronounced in glioma than in adjacent normal brain tissues." (PMID 38461458, 2024).
glioma (continued). "Finally, we verified that calycosin inhibited glioma growth in a xenograft mouse model and downregulated CXCL10 and its downstream molecules." (PMID 38461458, 2024). "However, in a paracrine manner, another study demonstrated that celecoxib enhanced overall CXCL10 expression in the glioma microenvironment through a decrease in myeloid-derived suppressor cells (MDSC), thus upregulating infiltration of CD8+ T cells into GBM." (PMID 38104126, 2023). "For example, CXCL10 plays a key role in inhibiting glioma growth." (PMID 37726303, 2023). "Gliomas in orthotopic syngeneic glioma mouse models bearing the IDH1 mutation compared with gliomas in mice wild type (WT) for IDH1 also have reduced tumor-infiltrating cytotoxic T cells, as well as reduced chemokine CXCL10 expression and reduced STAT1-positive cells." (PMID 35385679, 2022). "In parallel, glioma-associated macrophages are stimulated by glioma cells to produce tumor necrosis factor-α (TNFα), which activates the endothelial cell expression of the proangiogenic molecules (VCAM-1, ICAM-1, CXCL5, and CXCL10)." (PMID 35740307, 2022). "Reduced CXCL10 expression in gliomas from CD169-DTR mice was also confirmed at the protein level." (PMID 36266311, 2022). "Using RT-PCR, it was found that CXCL10 mRNA was expressed in GL261 glioma cells." (PMID 35269652, 2022). "This study mentions a variation of CXCL10 expression in different human glioma lines." (PMID 35269652, 2022). "Their orthotopic syngeneic glioma model demonstrated that IDH1 R132H mutation suppressed the STAT1 protein expression via 2-HG, thus decreasing the type 1-associated chemokines such as CXCL10 and affecting CD8+ T cell aggregation." (PMID 35769466, 2022). "Since T cells present in human PAs and Nf1 murine low-grade gliomas establish a supportive microenvironment for low-grade glioma growth in vivo, it is important to use host systems with immune systems with limited immunologic impairment, such as Cxcl10−/− mice." (PMID 35986378, 2022). "Furthermore, mutant IDH1 inhibitor led to increased survival in preclinical glioma models and led to increased CXCL10 expression and TILs." (PMID 35203421, 2022). "Compared to gliomas with wtIDH1/2, IDH-mutated gliomas show small numbers of tumor-infiltrating CD4+ and CD8+ T cells and a low expression of cytotoxic T-lymphocyte–associated genes and IFN-γ–inducible chemokines, including CXCL10." (PMID 34203535, 2021). "CXCL10 is being explored in combination with a glioma tumor vaccine (NCT02549833)." (PMID 34045467, 2021). "Moreover, we found that PDCD4 regulates the expression of IL-5, CCL-5, VEGF, and CXCL10 in glioma cells, which provides a therapeutic opportunity to block these cytokines." (PMID 33304903, 2020). "More work needs to be done to better understand the role of CXCL10 in glioma tumorigenesis." (PMID 25978454, 2015). "Our present study showed that CXCL10, in fact, was present in high concentrations in glioma-conditioned media and could potentially promote CTL migration out of the fibrin clot." (PMID 22496835, 2012). "Contrarily, other studies have indicated that upregulating CXCL10 could inhibit glioma progression." (PMID 38461458, 2024). "Hence, it can be inferred that reduced CXCL10 secretion may be heavily involved in IDH1-mutant glioma cells’ strategy to hamper CD8+ T cell chemotaxis." (PMID 35385679, 2022). "Consistent with the reduction of β-catenin abundance in AEG-1 silencing glioma cells, a large restraint of PD-L1 expression and an increased CXCL10 expression were observed, implying that AEG-1 may play a potentially broader role in tumor immune evasion which worth further investigation." (PMID 34462446, 2021). "In gliomas, CXCL10 upregulation may promote the recruitment of T cells." (PMID 33960680, 2021).
glioma (continued). "Previous work has also demonstrated that endogenous CXCL10 could inhibit glioma development and promote tumor infiltration of CD8+ T cells in transgenic mice; additionally, myeloid-derived suppressor cells (MDSCs) produce CXCL10, indicating that they are pleiotropic." (PMID 25978454, 2015). "The cytokine-cytokine receptor pathway featured 35 genes (p = 3.79 × 10−7), such as CCL5, CXCL10, and IFNG, indicating impaired chemokine-mediated immune cell recruitment (e.g., CD8+ T cells and macrophages) in the immunosuppressive glioma microenvironment." (PMID 40406701, 2025). "As expected, the conditioned medium from either GL261 or ALTS1C1 glioma cells significantly activated BV2 cells with a notable increase in pro-inflammatory cytokines, including IL-6, CCL-2, CXCL-10, MMP-14, TNFα, IL-1β, and iNOS." (PMID 41367876, 2025). "Recent evidence has shown that the activation of RIG-I promotes apoptosis in gliomas and increases the production of IFN-β and CXCL10, thereby inhibiting the tumor growth in both in vitro and in vivo models." (PMID 40958871, 2025). "CXCL10 will recruit CD8+ T cells to infiltrate around glioma lesions and activate the immune response of glioma." (PMID 39429695, 2024). "Most of the chemokines that have been shown to regulate glioma angiogenesis, such as CXCL9 and CXCL10, are highly expressed in cluster B." (PMID 38181024, 2024). "In a murine model with glioma, ferritin-assembled NP loaded with SR717 improved IFN-β, TNF-α, CXCL-9, and CXCL-10 expressions in TME." (PMID 38185685, 2024). "SRGN-expressing glioma cells after co-culture with mast cells further enhance their expression of SRGN, CD44, CXCL-10, CXCL-12 and TNFα as well as EMT-related genes ZEB-1 and vimentin." (PMID 38672477, 2024). "Our results demonstrated a correlation between high levels of WDHD1 expression and positive CXCL10 and CXCL5 in gliomas." (PMID 38980253, 2024). "The reshaped TAMCs further affected the landscape of adaptive antitumor immunity in glioma TME and featured activation of CD8+ T cells along with increased levels of CXCL10 and CCL2." (PMID 38185685, 2024). "GSK343 inhibitor induces glioma cell apoptosis and increases CXCL9, CXCL10, and CXCL11 expression in the GBM environment." (PMID 38104126, 2023). "Then, we selected the top 5 relevant immunomodulators, including an immunostimulator (CD276), two immunoinhibitors (IL10RB and TGFBR1), a chemokine (CXCL10) and an MHC (HLA-A), in the glioma dataset and drew scatterplots to show their details." (PMID 37006287, 2023). "These immune cells had the highest density in gliomas and possessed immunosuppressive cytokines and chemokines, including CXCL12, CXCL10, CCR5, CCR10, CCL5, and CCR2, to exert their immunosuppressive effects." (PMID 37515314, 2023). "CXCL10 is expressed in murine glioma GL261 cells in vitro, while CXCL9 and CXCL10 are expressed in vivo in GL261 tumors." (PMID 35269652, 2022). "Co-culture of mast cells with glioma cells induces the expression of serglycin, CD44, ZEB1, vimentin, CXCL10, CXCL12, and TNF-α in glioma cells and IL-6 and CXCL1 in mast cells, creating an inflammatory milieu that induce glioma cell aggressiveness." (PMID 35494005, 2022). "Levels of the Ifnb1, Cxcl9, Cxcl10 and TNF-α mRNAs in glioma tissues from different treatment groups were determined using qRT-PCR to evaluate the activation of STING signaling." (PMID 35386310, 2022). "In a mouse glioma model, brain tumor-infiltrating macrophages also expressed CD169 and produced the proinflammatory chemokines CXCL9, CXCL10, and CXCL16." (PMID 36266311, 2022). "CXCR3 signaling mediated by CXCL9, CXCL10, CXCL11 and CXCL4 plays a major role in inflammation and immunopathology as well as in prohibiting angiogenesis in gliomas." (PMID 34203660, 2021).
glioma (continued). "TIME cluster A exhibited the high expression profiles of ZEB1, TNF, and LAG3; while GZMA, CXCL9, CXCL10, and CD8A were relatively overexpressed in TIME cluster C. EMT is a common process of paramount importance in glioma occurrence and invasion." (PMID 34650972, 2021). "CXCL10, CCL13, SAA1, and CCL27 were more highly expressed in elderly, high‐grade, 1p19q non‐codel, IDH‐wildtype glioma patients, while SSTR5, CCL21, and HTR1A expressions were low in these malignant clinicopathological features of gliomas." (PMID 33503296, 2021). "Although glioma does express CXCL10, this is accompanied by the expression of dipeptidylpeptidase (DPP)-4, which cleaves CXCL10." (PMID 34771532, 2021). "In this study, CXCL10 and CCL2 chemokines displayed the most significant effects on the attraction and migration of glial tumor cells in vitro, as well as in vivo in the F98-Fischer rat model." (PMID 34830041, 2021). "An alternative approach to inducing expression of CXCL10 is the use of poly-ICLC, which has been found to significantly increase the frequency of TILs when combined with peptide vaccination against glioma." (PMID 34771532, 2021). "The injection of c-di-GMP into a newborn glioma model can improve the survival rate of glioma-bearing mice in a STING-dependent manner, such as enhancing the signal of IFN-1, CXCL10, and the migration of T cells to the brain." (PMID 35046953, 2021). "In the training cohort, CXCL14 (P value < 0.001), CXCL9 (P value < 0.05), CXCL10 (P value < 0.001), CXCL11 (P value < 0.001), CXCL6 (P value < 0.001), and CXCL1 (P value < 0.001) were enriched in the IDH wide-type gliomas." (PMID 34603309, 2021). "In gliomas, abnormal expression profiles of CXCL9, CXCL10, CXCL11, and CXCL12 were noticed among different pathological grade gliomas, implying their potential relationship with glioma progression." (PMID 34603309, 2021). "In this work, CXCL9, CXCL10, and CXCL14 were also identified as potential vital regulators of glioma progression among the CXCL family." (PMID 34603309, 2021). "obtained that LncRNA-135528 up-regulates the expression of CXCL10 through JAK/STAT signaling pathway, thereby inhibiting the development of glioma." (PMID 33330055, 2020). "We inhibited the expression of BMPER, CXCL10, and HOXA9 using siRNA in the 2 cases of glioma stem cell spheres." (PMID 32432046, 2020). "In summary, in primary high-grade gliomas, BMPER, CXCL10, and HOXA9 expression can promote early-phase tumor growth and further progression by increasing tumor neovascularization." (PMID 32432046, 2020). "Other studies also showed that CXCL10 and HOXA9 expression levels were elevated in some glioma tissues." (PMID 32432046, 2020). "We observed decreased overall expression and activation of signal transducer and activator of transcription 1 (STAT1) and significantly lower levels of the effector T-cell attracting chemokines, such as CXCL10, produced by IDH-mutant glioma cells." (PMID 30740109, 2018). "In our study, we observe a marked increase in the expression of CXCL10 and CXCL12 in the glioma cells after co-culture as compared to normal culturing of glioma cells." (PMID 28445977, 2017). "A recent study demonstrates that CXCL10 and its receptor, CXCR3, are upregulated in human glioma cells." (PMID 26506595, 2016). "Of interest, both in vitro and in vivo experiments using different glioma tumors, including GL261 cells, indicated CXCL9 and CXCL10 (which bind to their endogenous receptor CXCR3) as key ligands promoting the growth of glioma." (PMID 26157361, 2015). "Our findings reveal OLIG2+ glioma stem-like cells as critical mediators of immune evasion and identify the OLIG2/HDAC7/CXCL10 axis as a potential therapeutic target to enhance immune checkpoint inhibitor efficacy and improve immunotherapy outcomes in aggressive GBMs." (PMID 41591814, 2026). "CXCL10 levels were elevated (compared with those in naïve mice) in the brains of glioma-bearing mice independent of treatment." (PMID 40281508, 2025).
glioma (continued). "Moreover, we found that R-2HG regulates the glioma microenvironment by decreasing IL-6, CCL2, CXCL10, and MMP-14 in microglia." (PMID 41367876, 2025). "Finally, the local release of CXCL10 by nanomaterial hydrogels recruits activated CD8+ T cells and induces the apoptosis of metastasizing glioma cells." (PMID 38104126, 2023). "CXCL10 activated CXCR3+ effector T cells, which stimulated T cells to release more CXCL10, further enhancing the chemoattraction of CXCR3+ T lymphocytes and antigen-specific cytotoxic T lymphocytes to gliomas." (PMID 38104126, 2023). "In addition, the levels of CXCL9, CXCL10, and CCR3, which increase the recruitment of CD8+ T cells into the microenvironment of glioma, were increased in gliomas with high TANK expression." (PMID 37215097, 2023). "Whereas human pediatric PA cells did not form gliomas in wild type mice, both Rag1−/− and Cxcl10−/− mice developed LGGs at 1mpi and 6mpi." (PMID 35986378, 2022). "Chemokine CXCL10 expression and enrichment of gene set related to macrophage migration in CD169+ macrophages indicated the contribution of CD169+ macrophages to immune cell infiltration into glioma." (PMID 36266311, 2022). "Likewise, our in vitro experiments show the significant role of CXCL10 as a promoter of chemoattraction for F98 and U87MG glial tumor cells." (PMID 34830041, 2021). "CXCL9, CXCL10, CXCL11, CXCL12, and CXCL14 were filtered as main contributors of glioma progression." (PMID 34603309, 2021). "Therefore, BMPER, CXCL10, and HOXA9 can be used as novel targets for antiangiogenic treatment of primary high-grade gliomas." (PMID 32432046, 2020). "Transcriptome sequencing results confirmed that the expression levels of BMPER, CXCL10, and HOXA9 in the cases that could form orthotopic xenograft glioma models were significantly higher than those in the cases that could not form xenografts." (PMID 32432046, 2020). "ROC curve analysis indicated that the scanning parameters rCBV, rCBF, Ktrans, and Vp of the DSC-MRI and DCE-MRI can be used as imaging markers to predict the expression statuses of BMPER, CXCL10, and HOXA9 in tumor tissue, which can guide the antiangiogenic treatment of primary high-grade gliomas." (PMID 32432046, 2020). "In GSCs, celecoxib revealed significant decrease in mRNA levels of Ccl2 and Cxcr3 but not of Ccr2 and Cxcl10, which was consistent with the high mRNA levels of Ccl2 in the glioma model and GSCs but none of Cxcl10 in GSCs." (PMID 32943658, 2020). "In the two glioma surgical specimen groups, the expression levels of BMPER, CXCL10 and HOXA9 in the surgical specimens that could form xenografts were significantly higher than those in the surgical specimens that could not form xenografts." (PMID 32432046, 2020). "Here, we studied the importance of paracrine signaling in the glioma microenvironment by focusing on the celecoxib-mediated role of chemokines C–C motif ligand 2 (CCL2), C-X-C ligand 10 (CXCL10), and their receptors, CCR2 and CXCR3, in GSCs and a GSC-bearing malignant glioma model." (PMID 32943658, 2020). "We observed that the expression of apoptosis-related factors (cleaved caspase 3 and Bad) was lower, while the expression of anti-apoptosis (Bcl2), invasion (MMP2 and MMP9) and chemokine pathway related factors (CXCL10 and CXCR3) was higher in glioma tissues than in normal tissues." (PMID 26506595, 2016). "In our study, TREM2 knockdown significantly suppressed the expression of CXCL10 and CXCR3, which could be interpreted as anti-proliferation and anti-invasion effects of TREM2 siRNA in glioma cells." (PMID 26506595, 2016). "Indeed, an increased proliferation of malignant glioma cells compared with normal astrocytes and an anti-apoptotic effect in CXCR3-A-overexpressing human myeloma cell lines (HMCLs) was observed after CXCL10 treatment." (PMID 31216755, 2019). "The role of IP-10 (CXCL-10) has not been well studied in relation to progression of gliomas." (PMID 26755664, 2016).